RAD51 (RAD51 recombinase)
Diseases named in the same sentence as RAD51 in open-access papers (continued):
Sharing a sentence is not in itself a finding about the gene and the disease.
glioma (continued). "Therefore, FEN1 is a key regulator of BRCA1 and RAD51 protein levels and function in glioma cells." (PMID 35414100, 2022). "In addition, 53BP1 and Rad51 are important for glioma tumorigenesis." (PMID 30953555, 2019). "RAD51 was also positively correlated with most MHC molecules in liver hepatocellular carcinoma (LIHC) and low-grade glioma (LGG)." (PMID 35359409, 2022). "While RAD51AP1 is known to promote RAD51-mediated homologous recombination, the role of RAD51AP1 in glioma has rarely been studied." (PMID 31532757, 2019). "Inhibition of Rad51 and MPG has been described to sensitize glioma cells to other agents, such as TMZ, a drug that is commonly used to treat brain tumors, opening new therapeutic combination options." (PMID 31036068, 2019). "We observed the inhibition of proteins that play a main role in double strand break repair, such as Rad51, MPG and proteins that are part of the MRN complex, in pediatric glioma cells infected with Delta-24-RGD." (PMID 31036068, 2019). "Fibronectin, Rad51, Cyclin-E1 and Progesterone Receptor are also shown, along with supporting box plots from the IDH-wt grade II/III glioma vs GBM expression data, and demonstrated higher expression in the PN and GBM samples." (PMID 29142297, 2017). "Increased H2AX phosphorylation, caspase-3 cleavage, reduced Rad51 and RIP1 expression, as well as sustained IκBα expression were also observed in mouse glioma xenografts treated with the cyclo-RGD inhibitor and TMZ, confirming the molecular mechanism in vivo." (PMID 27487141, 2017). "For instance, targeting RAD51-dependent repair together with ionizing radiation and TMZ has been reported to be an effective therapeutic strategy for glioma." (PMID 25337721, 2014). "Given the findings that HR-DNA repair proteins (BRCA1, BRCA2 and RAD51) are significantly increased in TMZ-resistant glioma cells, an abundance expression of BRCC3 in glioma cells seems likely to foster HR-dependent DNA repair processes." (PMID 25337721, 2014). "Additionally, the mRNA expression levels of MST4/STK26, USP14, and ALKBH5 were positively correlated with ALKBH5 target genes, including FANCD2, FANCI, MKI67, and RAD51 within the TCGA and CGGA glioma datasets." (PMID 39990235, 2025). "By preferentially activating the DNA damage checkpoint response to control the cell cycle, boost DNA repair capacity, and decrease radiosensitivity by upregulating the expression of HR genes RAD51-, BRCA1/2-, and CD133-positive glioma stem cells help to develop glioma radioresistance." (PMID 37322433, 2023). "The prognostic power of RAD51 in glioma has not been reported, as in most of the studies, high- and low-grade glioma were studied separately." (PMID 35359409, 2022). "We labeled FEN1, BRCA1 and RAD51 in glioma mouse samples and observed decreased BRCA1 and RAD51 expression upon treatment with the specific FEN1 inhibitor sc13, confirming the regulatory role of FEN1 on BRCA1 and RAD51 in glioma cells." (PMID 35414100, 2022). "Since CHK1 and RAD51 are well-known players in homologous recombination and were also downregulated upon RHPS4 treatment, as previously reported in glioma cells; we decided to evaluate their levels, in order to gain insight in the recombinational mechanism activated." (PMID 32183119, 2020).
glioma (continued). "Representative images showed that 13 tissue types had a stronger staining signal of RAD51 in cancer than non-cancer tissues, including breast, liver, colon, cervix, stomach, pancreas, prostate, kidney, ovary, lung, glioma, head and neck cancer, and skin cancer and melanoma." (PMID 35359409, 2022). "Moreover, as FEN1 regulates the expression and function of many molecules, there may be additional effects of FEN1 inhibition that contribute to sensitization of glioma cells to DNA-PKcs dysfunction, either cooperating with BRCA1/2, RAD51 or WRN." (PMID 35414100, 2022). "Combination treatments of TMZ with ERK5i induced significant increases in cells exhibiting pDNA-PK nuclear foci over each treatment alone, which was not the case for RAD51 foci formation; a known contributing factor to cellular resistance to TMZ in glioma cells." (PMID 33668183, 2021).
triple-negative breast carcinoma (40 papers, 2011 to 2025). An invasive breast carcinoma which is negative for expression of estrogen receptor (ER), progesterone receptor (PR), and human epidermal growth factor receptor 2 (HER2). "An additional variant, RAD51 G151D, was found in a triple-negative breast cancer, but remarkably, this mutation leads to overactivation of RAD51 activity instead of inactivation." (PMID 34316706, 2021). "Two single nucleotide polymorphisms of XRCC2-41657C/T, and RAD51-172G/T were investigated in the reported study, as well as their association with human triple- negative breast cancer." (PMID 25743260, 2015). "What are important, recent reports introduce the role of RAD51 135G/C polymorphism in the development of triple-negative breast cancer." (PMID 25743260, 2015). "In our earlier study, RAD51 135C allele variant was associated with an elevated risk of triple-negative breast cancer in the Polish women." (PMID 24728564, 2015). "Enhanced TH-302 activity was also observed in Rad51 knockout cell lines and in triple-negative breast cancer cell lines exhibiting an HDR-deficient (BRCA-like) phenotype." (PMID 25994202, 2015). "It was found that the RAD51 polymorphism rs1801320 is associated with an elevated risk of breast and triple-negative breast cancer and ovarian, endometrial, colorectal, gastric, and head and neck cancer and myelodysplastic syndrome, as well as keratoconus and Fuchs endothelial corneal dystrophy." (PMID 26339569, 2015). "However, a study on a large series of triple-negative breast cancers showed that high miR-155 levels decreased the efficiency of homologous recombination repair by targeting the recombinase RAD51 and thus were associated with better overall survival of patients." (PMID 35925680, 2022). "It was obtained that the rs1801320 SNP in RAD51 is correlated with an increased risk of ovarian, breast, colorectal, endometrial, head and neck, myelodysplastic syndrome, Fuchs and keratoconus endothelial corneal dystrophy, as well as triple-negative breast cancer in several ethnicities." (PMID 34319032, 2021). "RAD51 is a potential biomarker and attractive drug target for metastatic triple negative breast cancer." (PMID 35563727, 2022). "Pathogenic germline mutations in the RAD51 paralog genes RAD51C and RAD51D, are known to confer susceptibility to ovarian and triple-negative breast cancer." (PMID 34635660, 2021). "Expression of RAD51 was progressively increasing in luminal, Her2-positive and triple-negative breast cancer tissues comparing with normal breast tissues." (PMID 31506496, 2019). "-61G>T in the RAD51 gene seems to affect the development of breast and triple-negative breast cancer, acute myeloid leukemia, and head and neck cancer." (PMID 26339569, 2015). "We believe our findings have clinical implications for treating aggressive metastatic triple negative breast cancer and other cancers that have acquired overexpression of RAD51 and is the focus of ongoing work." (PMID 24811120, 2014). "RAD51 is a potential biomarker and attractive drug target for metastatic triple negative breast cancer, with the capability to extend the survival of patients, which is less than 6 months." (PMID 24811120, 2014). "Furthermore, rare missense variants within PALB2 domains WD1, domain for stimulation of POLH DNA synthesis and domain for interaction with RAD51, BRCA2 and POLH were significantly associated with increased risk of triple-negative breast cancer." (PMID 37790698, 2023). "In conclusion, the obtained data confirm the important role of RAD51 172G/T - but not of -41657C/T of XRCC2 gene polymorphism in triple-negative breast cancer aetiology." (PMID 25743260, 2015). "However, gemcitabine has been shown to induce H2AX phosphorylation and Rad51 nuclear foci formation, i.e. markers of DNA double strand breaks, at stalled replication forks in triple-negative breast cancer cells." (PMID 21771338, 2011).
triple-negative breast carcinoma (continued). "Knocking down SPAG5 increased the S-phase cell population and decreased the expression of c-MYC target genes, including the DNA repair proteins RAD51 and BRCA1/2 in triple-negative breast cancer." (PMID 36304306, 2022). "Studies have shown that triple negative breast cancers (TNBCs) have enriched HDR defects, namely defective RAD51 formation, and increased chromosomal aberrations." (PMID 27630665, 2016). "HORMAD1 has been identified as a driver of genome instability in triple-negative breast cancers by suppressing RAD51-dependent HR, leading to increased reliance on nonhomologous end joining pathways." (PMID 40918650, 2025). "Consistent with the fact that RAD51AP1 functions in both luminal ER-positive and triple-negative breast cancers, EMP3 affects RAD51 expression as well as DNA replication, DNA damage repair, and stem-like properties in both ER-positive MCF7 and triple-negative MDA-MB-231/HS578 cells." (PMID 34511602, 2021). "When applied to a triple-negative breast cancer (TNBC) microarray dataset, the top selected modules contain both known gene markers in TNBC and novel candidates, such as RAD51 and DOK1, which play a central role in their respective ego-networks by connecting many differentially expressed genes." (PMID 24773628, 2014). "The obtained results indicate that the polymorphism of RAD51, but not of XRCC2 gene, may be positively associated with the incidence of triple-negative breast carcinoma in the population of Polish women." (PMID 25743260, 2015). "The polymorphisms of the XRCC2 gene -41657C/T (rs718282) and of the RAD51 gene, −172G/T (rs1801321), were investigated by PCR-RFLP in 70 patients with triple-negative breast cancer and 70 age- and sex matched non-cancer controls." (PMID 25743260, 2015).
colorectal cancer (37 papers, 2014 to 2025). A primary or metastatic malignant neoplasm that affects the colon or rectum. "In KRAS mutation-driven colorectal cancer, Rad51 has been reported to be transcribed by the KRAS downstream target MYC and to participate in the irradiation-induced DNA damage response and repair." (PMID 34215272, 2021). "A Polish case-control study was outlined that polymorphism of the RAD51 can alter the colorectal cancer risk alone as well as with association with other polymorphisms: XRCC2 gene." (PMID 32458654, 2020). "RAD51 overexpression has been linked to poor overall survival in colorectal cancer and identified as one of the most predictive factors in preoperative chemoradiation therapy for advanced rectal cancer." (PMID 28173629, 2017). "As claimed by the consequences of meta-analysis, the RAD51 135 G/C polymorphisms might influence colorectal cancer risk." (PMID 32458654, 2020). "Other data has shown that GC heterozygote of the RAD51 polymorphism may be associated with the increased risk of colorectal cancer development." (PMID 25247297, 2014). "Finally overexpression of RAD51 has also been linked with poor outcome in colorectal carcinomas." (PMID 28968952, 2017). "In agreement with the presence of basal replication stress in human colorectal cancer cells, RAD51 inhibition reduced replication fork speed in these cells and increased γH2Ax foci under control conditions." (PMID 35969531, 2022). "Accordingly, K‐RAS‐mutant colorectal cancer cells are highly dependent on RAD51 and HRR for survival." (PMID 35567502, 2022). "It has been reported that expression of the HR proteins MRE11 and RAD51, monitored by immunohistochemistry predicts the response and prognosis of colorectal cancer patients who received oxaliplatin chemotherapy." (PMID 34201502, 2021). "So, the association of RAD51 (rs1801320) and XRCC2 (rs3218536) genes polymorphism with colorectal cancer risk is observed in Bangladeshi population." (PMID 32458654, 2020). "In case of Bangladeshi population, no report is observed till now showing the genetic variations of RAD51 (rs1801320) and XRCC2 (rs3218536) genes polymorphism having association with colorectal cancer risk." (PMID 32458654, 2020). "So, it can be said that a significant association between RAD51 (rs1801320) and XRCC2 (rs3218536) and colorectal cancer development is confirmed in our population." (PMID 32458654, 2020). "We, consequently, presume to find out that predictable relationship of RAD51 (rs1801320) and XRCC2(rs3218536) genetic polymorphisms with colorectal cancer risk in Bangladeshi citizenry for the very first time." (PMID 32458654, 2020). "We recently reported that the CHK1 inhibitors PF-477736 and prexasertib attenuated F10-induced RAD51 activation in colorectal cancer cells." (PMID 31492187, 2019). "Collectively, our data suggest that KRAS‐ or BRAF‐mutant colorectal cancer lines are likely selectively dependent on Ras‐mediated RAD51‐dependent HRR signaling for survival." (PMID 28173629, 2017). "While inhibition of constitutive ERK1/2 signaling has limited effect in KRAS‐mutant colorectal cancer patients due to compensatory pathway activation, we found that combined inhibition of RAD51 and MEK1/2 significantly increases apoptosis by inducing DSBs." (PMID 28173629, 2017). "Our work now reports that FGFR4 enhanced the response of human colorectal cancer cells to radiation therapy by upregulating RAD51 and consequently increasing HR capacity." (PMID 27650548, 2016). "And indeed, our results show that colorectal cancers express higher levels of Rad51 and BRCA2 than normal mucosa." (PMID 25909291, 2015). "Rad51 overexpression showed inverse correlation with survival in patients with colorectal cancer and head and neck cancer perhaps arguing against a direct role in tumor cell resistance to therapy." (PMID 25909291, 2015). "In colorectal cancer, cells with the KRAS mutation are highly dependent on RAD51 for survival." (PMID 36262061, 2023).
colorectal cancer (continued). "A possibility may arise basing on a correlation between RAD51 (rs1801320) and XRCC2 (rs3218536) polymorphisms with colorectal cancer risk in Bangladeshi population." (PMID 32458654, 2020). "Therefore, RAD51(rs1801320) and XRCC2 (rs3218536) genes polymorphism and colorectal cancer risk is an important research area that needs much more attention as some statistically strong risk factors required to be excluded because of a small number of sample and control." (PMID 32458654, 2020). "The high levels of RAD51 expression were most remarkable in TL+ hematogenic tumor cell lines, K562, Raji and Daudi, and also in MMR-defective colorectal cancer cell line, DLD-1." (PMID 36042341, 2022). "We first confirmed that knockdown of β‐catenin in the APC‐mutant colorectal cancer cell line COLO320HSR markedly reduced the expression of BRCA1, FANCD2, and RAD51." (PMID 33660437, 2021). "Here, we show that the RSR is efficient in primary CSCs from colorectal cancer (CRC-SCs), and describe unique roles for PARP1 and MRE11/RAD51." (PMID 33531658, 2021). "To benchmark response, we included HR and RAD51 recruitment defective CAPAN1, and HR and RAD51 recruitment competent colorectal carcinoma HT29 cells." (PMID 34862364, 2021). "In summary, studying SNP in RAD51 (rs1801320) and XRCC2 (rs3218536) genes helps to recognize the malfunction of these proteins and can lead to successful therapies for colorectal cancer." (PMID 32458654, 2020). "Therefore, we studied the RAD51 mRNA expression levels in colorectal cancer (CRC), and evaluated the clinicopathological and prognostic significance of RAD51." (PMID 31973027, 2020). "RAD51 foci formation in ARID1A-proficient colorectal carcinoma (CRC) cell lines was not affected, except for HTC116." (PMID 31796878, 2019). "Targeting RAD51, a downstream effector of homologous recombination repair (HRR) or CHK1 inhibition, thus may offer a novel strategy in killing mutant KRAS‐dependent colorectal cancers." (PMID 28173629, 2017). "To better understand the relevance of this homologous recombination protein during the S phase, we analyzed the consequences of disrupting RAD51 during replication in non-transformed human cells and human colorectal cancer (CRC) cells, which have basal replication stress under control conditions." (PMID 35969531, 2022).